JUN (Jun proto-oncogene, AP-1 transcription factor subunit)
Diseases named in the same sentence as JUN in open-access papers (continued):
Sharing a sentence is not in itself a finding about the gene and the disease.
tumor (continued). "The CCK8 assay indicate that increased JUN expression can promote tumor cells proliferation, but by silencing PTX3 expression can reverse that process." (PMID 32984316, 2020). "The reduced production as well as the activation of c-JUN protein induced by LCL-PLP in the combined therapy has the potential to decrease the metastatic potential of the tumor cells via the inhibition of MMP-2 activation." (PMID 32340166, 2020). "AP-1 transcription factor complex (composed of FOS and JUN proteins) has been identified as the main determinant in tumor progression, proliferation, migration, invasion, angiogenesis, and drug resistance." (PMID 32296574, 2020). "FBXW7 is considered as a potent tumor suppressor as most of its target substrates can function as potential growth promoters, including c-Myc, Notch, cyclin E, c-JUN, and KLF5." (PMID 30791487, 2019). "c-JUN, which is also an ERK responsive gene, was regulated in the opposite direction as EGR1. rHE4 treatment upregulated expression of c-JUN, which is consistent with its role as a promoter of tumor growth and proliferation." (PMID 31164954, 2019). "A study of NPC tumor specimens found that tumor-suppressing protein PDCD4 suppresses the pPI3K/pAKT/c-JUN signaling pathway, which in turn modulates miR-374a's binding to CCND1, resulting in dysregulation of NPC cell growth, metastasis, and chemoresistance." (PMID 31456943, 2019). "For example, despite having been identified as a potent oncogene and tumour promoter, c-JUN is responsible for inducing apoptosis in UV-exposed cells." (PMID 29597249, 2018). "Immunohistochemical staining result in FOXO1-overexpressing tumor tissues of mice showed decreased expression of c-JUN." (PMID 30618730, 2018). "AP-1, which becomes active via phosphorylation of c-JUN by JNKs, is a crucial component involved in the expression of tumor-supportive cytokines and chemokines." (PMID 27894105, 2017). "The tumor-specific MELK interaction with the JNK/c-JUN is likely one of the mechanisms for the selective apoptosis that occurs as a result of MELK inhibition in GBM stem cells, but not in normal progenitors." (PMID 26973435, 2016). "Evidence from several different tumor models indicates that JUN is an important phosphorylation target of JNK during carcinogenesis." (PMID 26134322, 2015). "For instance, miRNAs-15a/16 cluster, considered a tumor suppressor found deleted in different malignancies, or miR-155 reported as repressor of JUN in human dermal fibroblasts in vitro." (PMID 25077705, 2014). "Conversely, activation of the PI3K/AKT and inhibition of JUN/MAPK pathways overrules the tumor suppressive effect of FOXOs and allows G1 progression." (PMID 23805779, 2013). "A second major effect of PI3K/AKT pathway activation and JUN/MAPK inhibition is on the metabolism of the tumor-initiating cells." (PMID 23805779, 2013). "The status of ERK, JNK, c-MYC and c-JUN were also compared in xenograft tumor tissues by immunohistochemical staining." (PMID 23650533, 2013). "In contrast, stable expression of a c-JUN deletion mutant (TAM67) in two malignant mouse epidermal cell lines blocked tumor formation in nude mice." (PMID 22312244, 2012). "Based on our studies we postulate a novel mechanism for how c-JUN accelerates leukemogenesis and regulates genes required for cell cycle progression in tumor cells." (PMID 21789792, 2011). "Since the initial discovery of v-JUN, solid evidence has accumulated linking AP-1 members and in particular c-JUN to tumor development." (PMID 21789792, 2011).
tumor (continued). "We suggest that the transcription factors SMAD3/4, GNB2L1/RACK1, MYC, MAX and JUN, whose functions have been extensively studied in tumours but only marginally in muscle, appear instead to play important roles in regulating muscle response to atrophy." (PMID 19108710, 2008). "In turn, the transactivation of β-catenin increases the transcription of genes that promote tumor cell growth, such as MYC, CCND1 (which encodes cyclin D) and JUN." (PMID 17764575, 2007). "Genes of this pathway up-regulated in CC tumor cells were JUN, MYC, FZD2, RAC1, GSK3B and CTNNB1, and a few others." (PMID 17822553, 2007). "Median survival was shorter for patients with ERBB-1-, VEGF-, cyclin A-, FOS-, or JUN-positive tumours." (PMID 9484827, 1998). "The tumor growth of CRC is closely related to the phosphorylation of JUN." (PMID 41584725, 2026). "In summary, this study identified JUN, NFKB1, and SP1 as important biomarkers associated with stem cells and telomere maintenance mechanisms in BC, highlighting their critical roles in tumor progression, alterations in the immune microenvironment, and potential therapeutic targets." (PMID 40666524, 2025). "Together, this work demonstrates that FOS and JUN may function in coordinating the redox-steroidogenesis axis, linking molecular changes in the adjacent cortex to tumor function and microenvironmental remodeling." (PMID 41412035, 2025). "JUN promotes the self-renewal and stemness maintenance of cancer stem cells by activating stem cell-related pathways such as β-catenin and Notch and enhances tumor initiation ability and chemotherapy resistance." (PMID 40666524, 2025). "WPMY-1 cells, while sharing some TFs, showed higher activity of TFs associated with cell cycle regulation and proliferation, such as E2F family members (E2F1, E2F4, E2F8) and JUN, highlighting key regulatory differences between tumor-derived CAFs and benign stromal fibroblasts." (PMID 41198614, 2025). "Tumor-derived Gal-1 has been revealed to boost the proliferation and metastasis of gastric cancer cells via the neuropilin-1/c-JUN/Wee1 pathway and enhance nanoclustering of the H-Ras proto-oncogene through direct interaction with the Ras binding domain of Raf." (PMID 40178639, 2025). "However, JUN has also been extensively and very often described as a survival mechanism that suppresses cellular stress-mediated apoptosis and promoting tumor cell survival." (PMID 38263136, 2024). "Notably, JUN here reduced tumor growth despite its ability to block apoptosis (Fig. EV5A,B) in JUN-deficient livers." (PMID 39210147, 2024). "And the results disclosed that the protein expression of phospho-JNK, c-JUN, phospho-JUN, and tumor metastasis-related molecules (e.g., TWIST and SNAIL) was obviously enhanced in PANC-1/LINC00909-OE cells, whereas it was decreased in the PANC-1/LINC00909-KD and AsPC-1/LINC00909-KD cell lines." (PMID 38504385, 2024). "An unbiased drug screen identified the tyrosine kinase inhibitor dasatinib that potentiates MRTX849 efficacy by inhibiting SRC-dependent JUN activation, avoiding multidrug resistance and tumor suppression in vitro as well as in suitable preclinical mouse models and patient-derived organoids." (PMID 39661665, 2024). "The upregulation of activating transcription factors FOS and JUN was also detected in TRNA samples when compared to BPH samples, the expression of which has been previously linked to epithelial cell stress response in tumor progression." (PMID 39550375, 2024). "Assuming that JUN mediates tumor-suppressor activity via positive regulation of SASP factors required for the recruitment of immune cells, we expected that high levels of SASP factors may be associated with favorable prognosis." (PMID 38811984, 2024). "To test whether JUN’s ability to restrain tumor growth depends on NCOR1/2 expression, we cloned mirE-based tandem shRNA constructs targeting NCOR1 and NCOR2 into the myr-AKT-HA vector." (PMID 39210147, 2024).
tumor (continued). "Tumor cell migration is significantly influenced by JUN, which is up-regulated in GBM." (PMID 39850823, 2024). "This indicates that somatic SNVs in NOTCH1, JUN, and KDR genes may cause cancer cells to develop at various speeds and result in varying localized colonization of different cell types in the tumor." (PMID 38811597, 2024). "JUN is one of the most essential proto-oncogenes involved in cell growth and neoplasia." (PMID 37479693, 2023). "Interestingly, the same top-ranked motifs were bound by key TFs essential for tumor metastasis and invasion, including Fosl2 and JUN." (PMID 37479693, 2023). "First, UCSC Xena data showed that tumor tissues had higher JUN mRNA levels than normal tissues." (PMID 37310025, 2023). "Our study demonstrates that cadmium induces MTF-1 binding at FOS/JUN DNA motifs, suggesting a further role in tumor development and one mechanism of how cadmium exposure may transform cells." (PMID 36980293, 2023). "Interestingly, recent studies show that overexpression of JUN in T cells can reinvigorate T cells and improve anti-tumor potency." (PMID 37452307, 2023). "Taking impact of JUN in immunity to account, we envisaged that JUN may play a role in anti-tumor immunity and turned our sights to the expression of JUN in various cancer." (PMID 37986345, 2023). "In our female cohort, through MAPK signalling, higher expression of MAPK1/3 could result in anergy via JUN, which is reported to occur in T cells infiltrating tumours." (PMID 36826068, 2023). "Although beyond the scope of this work, it is tempting to speculate that FOSL1-mediated CEBPA depletion and reduced CEBPA-FOS/JUN interaction work in concert to promote tumor aggressiveness." (PMID 36631623, 2023). "Notably, JUN was the most significantly downregulated gene from tumor organoids of both RB subtypes." (PMID 36726110, 2023). "We speculate that sunitinib affects tumor proliferation and differentiation via downregulation of JUN for suppression of the RB growth." (PMID 36726110, 2023). "Nevertheless, when we performed immunohistochemical (IHC) analysis in tumor microarrays, we found that JUN protein levels are significantly higher in tumor stroma than paired para-cancerous stroma in all of the tested samples regardless of their TNM stages or metastasis states." (PMID 36438487, 2022). "Tumour-specific hypomethylation events were enriched in TF binding motifs of the JUN/FOS proteins, building blocks of the activator protein-1 (AP-1) transcription factor known for their role in lung tumorigenesis as well as their involvement within other signal transduction pathways." (PMID 35931677, 2022). "JUN appears to be important in the tumour development and growth of HCC28." (PMID 36351994, 2022). "JUN expression varied with tumor stages, and was positively correlated with OS." (PMID 36476606, 2022). "This is the first report on the role of JUN in the tumor microenvironment." (PMID 34421602, 2021). "Nevertheless, tumor xenograft models fostering a heterogeneous tumor microenvironment may be required for testing the antitumor effect of JUN inhibition, as the JUN activity is also elevated in tumor fibroblasts." (PMID 34459128, 2021). "To further validate whether the coinhibition of NF-κB and c-JUN could also exert synergistic antitumor effects in vivo, we established a tumor metastasis model by using zebrafish embryos xenografted with BEL-7402 HCC cells." (PMID 34395446, 2021). "For example, we describe JUN amplification that originated as a simple reciprocal translocation t(1:10) that underwent further breaking and rejoining (patient P1) as the primary tumor evolved (P1)." (PMID 33963544, 2021).
tumor (continued). "Furthermore, JUN is identified as potential transcription factor involves in pentraxin 3 mediated tumor cells autophagy." (PMID 32984316, 2020). "Both mRNA and protein levels of PD-L1 were significantly decreased in c-JUN-knockdown tumor cells." (PMID 32855386, 2020). "Similarly, in colon cancer, the expression of ODC, MAT2, FOS, and JUN in tumor tissues is higher than that in adjacent normal mucosa to provide polyamines for tumor cell proliferation." (PMID 33292222, 2020). "JUN plays an important role in transformation of liver from inflammation to tumor." (PMID 33224891, 2020). "However, like tumor cells, elevated transcription factor p-c-Jun is observed as response to the degradation of FBW7, and we have also shown direct E. chaffeensis TRP32 nucleomodulin-mediated upregulation of JUN expression during infection." (PMID 32353058, 2020). "Recently a miRNA targeting JUN has been identified as tumor suppressor." (PMID 33324443, 2020). "Other studies illustrated JUN serves as critical role in tumor progression." (PMID 32984316, 2020). "However, in recent years, contradicting evidence regarding the tumour suppressive role of c-JUN has emerged." (PMID 29597249, 2018). "This included rapid induction of histone hyperacetylation, indicating effective and specific inhibition of HDACs, and the transcriptional induction of ATF3 and JUN expression, two well-established target genes of HDACi, which have been shown to be induced by HDACi across a range of tumour types." (PMID 30562958, 2018). "As c-JUN appears to be a crucial mediator in propagating and maintaining a malignant phenotype, this study suggests that these interactions are significant for enhancing tumour–stroma interaction, adhesion and metastasis." (PMID 29597249, 2018). "The notion that multiple signaling pathways can activate JUN may explain why KRAS mutant tumor cells are traditionally seen as highly refractory to MEK inhibitor therapy." (PMID 30482246, 2018). "For example, in one patient treated with neoadjuvant gemcitabine and cisplatin with no response to treatment, rapid recurrence and short survival, we identified amplification in focal segments containing E2F3 and JUN (drivers of cell cycle progression) exclusively in the post-treatment tumor sample." (PMID 29259186, 2017). "The induction of c-JUN expression and activity leads to tumor progression and development." (PMID 27323831, 2016). "Here, JUN was downregulated in almost all tumor types in our pan-cancer analysis." (PMID 26655252, 2016). "JUN protein-based immunohistochemistry staining of tumor sections confirmed the mRNA results." (PMID 27648299, 2016). "The FOS/JUN/ETS2 plays important roles in tumor invasion and metastasis." (PMID 25137136, 2014). "Despite the unknown role of FOS in cancer-induced wasting, FOS heterodimerizes with c-JUN within the AP-1 transcription factor complex, which has been established as a factor required for muscle wasting in AH-130 tumor-bearing rats." (PMID 25539728, 2014). "This interaction and the mirror effect of the alterations on the two signaling pathways suggest that the PI3K/AKT pathway stimulates the growth of tumor cells whereas the JUN/MAPK pathway has an opposite effect and that the two pathways are the two sides of the same coin." (PMID 23805779, 2013). "Even though four (PIK3C2A, JUN, FNBP1, ITPR1) of our peripheral biomarkers have been implicated in cancer pathophysiology, none of the PBMC biomarkers were differentially expressed between tumor types (among all subjects, or within cases or controls alone)." (PMID 21884629, 2011).
tumor (continued). "LGALS3 regulated by SOX8/JUN complex was secreted by GSC into the tumour microenvironment, which could not only promote GBM MES transition by binding membrane protein ITGB1 on GSC in an autocrine form, but also promote immunosuppression by binding ITGB1 on TAM in a paracrine manner." (PMID 39629136, 2024). "However, besides myofibroblasts, we further identified the other two branches of differentiation for CAF and revealed that the number of CXCL12+ CAF was increased during tumor progression and became more fibrotic based on the expression of transcription factor JUN." (PMID 37360193, 2023). "In addition, our expression analyses showed that, among potential Mir34a targets, genes associated with the induction of STAT3, JUN and SRF expression signatures are presumably involved in the opposing regulation of intestinal homeostasis and tumor formation by Mir34a and Csf1r signaling." (PMID 36147476, 2022). "Therefore, IGF1 and JUN play important roles in dysregulation of Ras protein signal transduction, which may be related to aberrant tumor immunity in DLBCL." (PMID 33107145, 2021). "JUN might affect tumor progression through regulating PTX3 expression." (PMID 32984316, 2020). "To overcome tumor-driven CAR T cell suppression, we knock in c-JUN alongside a B7-H3 CAR into the TRAC locus of primary human T cells utilizing CRISPR-Cas9." (PMID 41564857, 2026). "JUN, FOS, STAT3, JUND and NR2F1 were up-regulated in clusters C2 and C3, leading to tumor progression and immune evasion by influencing target genes HSPA1A, CXCL9 and PDGFR." (PMID 42074110, 2026). "Genes associated with MAPK signaling cascades, a major downstream pathway of EGFR signaling (AREG, JUN, DNAJB1, DUSP1), were upregulated in tumor C0 NK cells." (PMID 41082397, 2026). "Proteomic signatures highlighted AREG, JUN, and ITGA6 can track skin damage, while CST5 and PRDX1 correlated with the preservation." (PMID 42143604, 2026). "When we focused on different expressed genes in a pathway related to tumor development, there were some important oncogenes correlated with JAM2, such as JUN, MMP1, CDH1, and so on." (PMID 39838844, 2025). "validated c-JUN as a downstream oncogene of PI3K/AKT, which regulates tumor migration, invasion, and metastasis by binding to genes upstream of PI3K/AKT signaling." (PMID 41293238, 2025). "Tumor-like fibroblasts exhibited elevated expression of stress-related genes ATF3 and JUN, which were enriched in the stress response and proliferation pathways." (PMID 40520021, 2025). "For a deeper understanding of the oncogenic mechanisms of the C0 MAFF+ tumor cell subtype, we analyzed the TFs within this subtype and identified the top five active TFs: KLF6, ATF3, JUN, FOS, and FOSB." (PMID 40936936, 2025). "Mechanistically, HMMR promotes tumor metastasis by interacting with MAP4K4, which in turn activates the p-JNK/p-c-JUN/MMP1 signaling pathway." (PMID 39990663, 2025). "Different studies in several human neoplasms, including CRC, showed higher c-JUN expression and activation in tumors compared to normal tissue." (PMID 40481178, 2025). "Mechanistically, HMMR promotes tumor metastasis by binding to mitogen-activated protein kinase kinase kinase kinase 4 (MAP4K4), which activates the p-JNK/p-c-JUN/MMP1 signaling cascade." (PMID 39990663, 2025). "The Wilcoxon rank sum test demonstrated significantly lower expression levels of JUN and EGFR in tumor samples compared to normal tissues, a finding further validated by paired sample comparisons." (PMID 41246859, 2025). "In the invasive edge, TFs such as FOS, JUN, and FOXC2 are likely driving epithelial-to-mesenchymal transition (EMT), enabling migration, invasion, and metastasis of tumor cells." (PMID 41238550, 2025).